DCST1 (DC-STAMP domain containing 1)
Description:
E3 ubiquitin-protein ligase which mediates 'Lys-48'-linked ubiquitination of STAT2 and induces its proteasomal degradation thereby negatively regulating type-I-interferon signaling. Essential sperm cell-surface protein required for sperm-egg fusion and fertilization (By similarity).
Synonyms: FLJ32785; SNKY; SPE49
Tractability: Antibody: UniProt places it where antibodies can reach, with high confidence; its Gene Ontology location is reachable by antibodies, with high confidence; UniProt predicts a signal peptide or a membrane-spanning region.
Gene: Protein-coding gene on chromosome 1 (155,033,824 to 155,050,930, forward strand). Ensembl gene ENSG00000163357.
Subcellular location: Cell membrane; Cytoplasmic vesicle, secretory vesicle, acrosome membrane
Subcellular location (Human Protein Atlas): Principal piece; Acrosome; Equatorial segment
Gene Ontology:
Molecular function: protein binding; ubiquitin protein ligase activity
Biological process: negative regulation of type I interferon-mediated signaling pathway; ubiquitin-dependent protein catabolic process; fusion of sperm to egg plasma membrane involved in single fertilization; sperm-egg recognition; protein ubiquitination
Cellular component: plasma membrane; acrosomal membrane; membrane
Genetic constraint (gnomAD): Loss-of-function variants: 78 observed, 91.26 expected, observed/expected ratio (o/e) 0.85, 90% interval 0.71 to 1.03. The upper end of that interval is the gene's LOEUF score, 1.03, which puts it in group 4 of 6, group 1 being the genes least tolerant of losing a copy. Missense variants: 900 observed, 946.84 expected, observed/expected ratio (o/e) 0.95, 90% interval 0.9 to 1. Synonymous variants: 364 observed, 377.1 expected, observed/expected ratio (o/e) 0.97, 90% interval 0.88 to 1.05.
Homologues: Orthologues: chimpanzee DCST1 (99% identical), macaque DCST1 (95% identical), pig DCST1 (84% identical), guinea pig DCST1 (84% identical), dog DCST1 (79% identical), rabbit DCST1 (76% identical), rat Dcst1 (75% identical), mouse Dcst1 (72% identical), zebrafish dcst1 (38% identical), Drosophila melanogaster snky (18% identical), Caenorhabditis elegans spe-49 (15% identical), Caenorhabditis elegans spe-42 (13% identical). Paralogues in human: DCST2 (23% identical), OCSTAMP (13% identical), DCSTAMP (13% identical).
Diseases named in the same sentence as DCST1 in open-access papers:
DCST1 is named in the same sentence as 5 diseases in open-access papers, as found by Europe PMC text mining. Sharing a sentence is not in itself a finding about the gene and the disease. The quoted sentences say what the papers report.
Infertility (1 paper, 2024). "Eight genes that result in male infertility (IZUMO1, SPACA6, TMEM95, TMEM81, SOF1, FIMP, DCST1, and DCST2) and an additional two that cause infertility in females (JUNO and CD9) have been identified." (PMID 38381819, 2024).
periodontitis (1 paper, 2024). An acute or chronic inflammatory process that affects the tissues that surround and support the teeth. "Furthermore, osteoclast activity was greatly enhanced by both F. nucleatum and its OMVs (middle row), and the expression of osteoclast markers, CTSK and DCST1, was increased by both F. nucleatum and its OMVs in rat periodontitis (lower two rows)." (PMID 39475060, 2024).
DCST1 also shares sentences with these, for which no sentence is quoted: hepatocellular carcinoma (1 paper); male infertility (1); Parkinson disease (1).